CD4 (CD4 molecule)
Diseases named in the same sentence as CD4 in open-access papers (continued):
Sharing a sentence is not in itself a finding about the gene and the disease.
tumor (continued). "These occurrences can lead to the suppression of CD4+ and CD8+ effector T cells that can no longer detect or respond to tumor antigens." (PMID 35463305, 2022). "The anti-tumor efficacy of NRTUAs is abrogated with the depletion of CD8+ and NK cells, but not CD4+ cells." (PMID 36118042, 2022). "The immunophenotype of typical ATLL tumor cells is positive for CD3, CD4, CD5, CD25, CCR4, and CADM1, and negative for CD7 and CD8." (PMID 35625999, 2022). "It is possible that a similar phenomenon occurs in the tumor setting and in the background of LEC MHC-II−/−, in which antigen-loaded LECs modulates CD4+ T cells in the TME not through direct antigen presentation but through elaboration of soluble factors." (PMID 36362253, 2022). "Neither CD4+ nor CD8+ T-cells showed increased IFN-γ, further supporting that the reduction in tumor burden was driven by the WGP-trained myeloid cells." (PMID 35140221, 2022). "Regardless of the tumor status, the higher infiltration with CD3+CD4+ (Th), CD3+CD8+ (Tc), and Treg cells was detected in the stroma, compared to the parenchyma (p < 0.0001 for all cell populations, data not shown)." (PMID 36359314, 2022). "When we knocked out both CD4+ and CD8+ T cells, the efficacy of triple therapy was still strong; although the treated tumours tended to grow, the difference was not obvious." (PMID 34731284, 2022). "Compared with treatment-naive tumor lesions, more intra-tumoral NK/NKT and CD4+ T cells were found in neoadjuvant non-MPR and MPR tumor lesions (NK/NKT: 2.36% versus 5.71% versus 5.72%; CD4+ T cells: 7.23% versus 14.05% versus 13.24%)." (PMID 35831283, 2022). "CD4+ Th cells, Treg, and DNT did not display a significant difference across the tumor progress of GC." (PMID 35874784, 2022). "Relevant studies have shown that CD8 + and CD4 + cells can infiltrate distal lesions independent of NK cells and IFN I, and even influence distal tumor cells with similar molecular structure, thereby achieving systemic anti-tumor immunity." (PMID 36467495, 2022). "The other attribute would be to overcome immune exhaustion and non-recruitment of effector CD4 and CD8 tumor-specific lymphocytes for desired abscopal effects." (PMID 35155221, 2022). "Previous studies found that CD4+, CD8+ TILs infiltration was substantially higher in tumors with more aggressive tumor behaviors, such as high grade, negative HR status, HER2 amplification, and high Ki-67 level." (PMID 36528658, 2022). "Despite mounting evidence has shown that CD4+ T cells play a major role in anti-tumor immunity, the role of the MHC-II molecules in tumor immunotherapy has not been thoroughly researched and reported." (PMID 35223828, 2022). "Cancer vaccination enhances tumor-specific CD4+ and CD8+ T cells, which eliminates tumor cells without affecting the normal cells." (PMID 35887235, 2022). "While we observed a slight decrease in the tumor-infiltrating CD8+ and CD4+ T cell populations, this reduction was not significant." (PMID 36439171, 2022). "After 48 weeks of WD, both the untreated control and the SP16 treated groups had one tumor-free animal and five tumor-bearing animals and the NAFLD-induced depletion of CD4+ T cells was independent of tumor burden." (PMID 36428596, 2022). "Briefly, tumor cells in AITL/FHTCL demonstrated a very characteristic immunophenotypic signature with positive expressions of CD2, CD4, CD5, CD45, and heterogeneous CD7 but negative expressions of surface CD3, CD8, CD16, CD56, CD25, CD26, and CD30." (PMID 35299754, 2022). "The 3 patients with tumor in the lymph nodes had a significantly lower percentage of CD3+ and CD4+ T cells compared to patients (n=10) found to have no tumor in the SLN (nSLN) (p=0.0245 and p=0.028, respectively)." (PMID 36052068, 2022).
tumor (continued). "Thus, in the model in which tumor-derived antigen could be presented to T-cell receptor-transgenic (TCR-tg) CD4+ T cells by host but not tumor MHC-II molecules, adoptive transfer of pre-activated CD4+ T cells was able to control the growth of tumors in some lymphopenic hosts." (PMID 36159781, 2022). "In contrast, the percentage of Ly-6G+ neutrophils, NK1.1+ NK cells, and CD3+ T-cells and its subtypes (CD4+ naïve and CD8+ cytotoxic T cells) in the tumor were not altered between Trib1mWT and Trib1mKO." (PMID 35664073, 2022). "In the saline group, no obvious infiltration of CD4+ and CD8+ T cell in the tumor tissues was observed." (PMID 36380062, 2022). "The CD4/CD8 ratio and programmed cell death-1 (PD-1) expression of T cells in primary tumor tissues, tumor-draining lymph nodes (TDLNs) and non-draining lymph nodes (NDLNs) were assayed with flow cytometry." (PMID 35633411, 2022). "We also noticed an increase in the cytotoxic CD4+ T cells, but no changes in the G‐MDSCs or Tregs in the TIME of the nontreated side tumor." (PMID 35243806, 2022). "For each tumor sample from the tumor-bearing mice after 7 days treatment with or without Nr-CWS, the percentage of infiltrated lymphocytes including CD3+, CD4+ T, CD8+ T, and NK cells, were analyzed by FCM." (PMID 36110249, 2022). "There were no significant alterations in the number of CD4+ T cells, CD8+ T cells and NK cells in tumours received with JQ1 treatment combined with radiation and cisplatin." (PMID 35083874, 2022). "The proportion of CD4 and IL-21 positive cells in MPR tumor tissues were also significantly higher than that in treatment-naive and non-MPR tumor tissues." (PMID 35831283, 2022). "A lack of alteration in T cell subsets is supported by previous transcriptomic analysis of stromal cells of KRas-driven mouse tumors, which found no change in the number of CD4+ and CD8+ T cell numbers between tumor and control tissue of the lungs." (PMID 35145525, 2022). "They found that in patients treated with these immunotherapeutic agents there is increase in the filtration of CD4+ and CD8+ cells without change or depletion of the FOXP3 cells within the tumor microenvironment." (PMID 35892890, 2022). "In keeping with NK-cell origin in many cases, the tumour stains positive for CD2, CD3ε, CD7, CD56, cytotoxic granules (TIA1, granzyme, perforin), CD158/KIR and CD335/NKp46 but is usually negative for sCD3, CD4, CD8, CD57 and TCR." (PMID 35626087, 2022). "Our study found that sTILS, CD45+, CD3+, CD4+, and CD8+ cells tended to have a higher frequency in tumor tissue (stromal) and that the frequencies of CD20+, FoxP3+ and CD68+ cells in tumor tissue did not change after-NAT compared with before-NAT." (PMID 35562400, 2022). "In conclusion, Tregs exhibit a distinct molecular pattern including activation and ICP molecules in comparison to CD4+ Tconv in TLS and non-TLS areas of the tumor." (PMID 36566320, 2022). "IHC staining of the tumor tissues proved that the infiltration of CD8+ T cells, but not CD4+ T cells, was significantly promoted by SZU251 + MUC1 + Al." (PMID 36499455, 2022). "Unlike wild-type mice, interferon-β treatment neither attracts CD4+ and CD8+ T cells to tumor sites nor suppresses tumor growth in Stat2-knockout mice." (PMID 35207629, 2022). "A previous study found that IRF1 was found to negatively regulate the function of CD4+CD25+ Treg cells by directly and specifically repressing the expression of FOXP3 gene, suggesting the negative correlation between IRF1 and FOXP3 in tumor immunity." (PMID 35664436, 2022). "For example, anti-CTLA-4 mAbs ipilimumab and tremelimumab were found to increase the density of CD4+ and CD8+ T cells in tumor tissues but not deplete Tregs." (PMID 35345849, 2022). "Th2 and Th17 CD4 T cells are not always considered a positive feature of tumor environments; however, patients with tumors expressing increased proportions of ICOS-expressing CD4 T cells have an improved prognosis." (PMID 36056093, 2022).
tumor (continued). "The tumor restraining effect was abolished by treatment with anti-CD1d, anti-CD8 or anti-CD4 antibody, whereas it was not affected when an isotype-matched IgG control was used." (PMID 34983554, 2022). "To understand the functional status of T cells in different treatment groups, we compared the DEGs of CD4+ and CD8+ T clusters in treatment-naive, non-MPR, and MPR tumor lesions." (PMID 35831283, 2022). "In addition, whether antigen-specific memory CD4+ T cells can prevent tumor metastasis and respond to PD-1 signaling blockade therapy has not been fully elucidated, and the possibility that CD4+ T cells can become exhausted during tumor progression remains a matter of debate." (PMID 35784297, 2022). "TIGIT and TIM-3 inhibitory receptors were specifically increased in TIL and not in NIL CD4 and CD8 T cells, suggesting that the tumor microenvironment plays a crucial role in inhibiting tumor-specific T-cell responses." (PMID 36341402, 2022). "We observed significant increases in IL-17 expression by both CD4+ and CD8+ T-cells in the spleens and lymph nodes of tumor-bearing Pik3cg−/−, though not in the tumor." (PMID 33668795, 2021). "Combined numbers of CD4 and CD8 TILs in the tumor center or stroma were rather similar, regardless of MSI status." (PMID 34680397, 2021). "A tumor biopsy was performed, and the histological findings of the tumor lesion showed a proliferation of tumor cells that were positive for myeloperoxidase and CD68 and negative for CD4 and CD123." (PMID 33976945, 2021). "The TMNPs promoted the tumor infiltration of CD3+ T cells by 2-fold, including memory/effector CD8+ T cells (4.2-fold) and CD4+ (1.7-fold), but not regulatory T cells." (PMID 34959271, 2021). "While the CD3+ and CD8+ tumor infiltrate was increased in the RGS-treated tumors, there was no significant alteration in the level of CD4+FoxP3+ T regulatory cells (Tregs) or angiogenesis (CD31)." (PMID 34092233, 2021). "As our previous studies have shown, RFS was also correlated with PD-L1 on TILs, and CD3, CD4, CD8, and FOXP3 on immune cells but not with PD-1 on TILs and PD-L1 on tumor cells." (PMID 34362829, 2021). "The dosages of the radiopharmaceuticals and αPD-L1 antibodies were reduced, the infiltration of CD4+ and CD8+ T cells in the tumor microenvironment was increased, and no side effects were observed." (PMID 33391476, 2021). "We observed significant enriched of CD8+CD45+ and CD4+CD45+ T cells in DR5 agonist‐treated tumors regardless of ROCK1i and avelumab co‐treatments (n = 6–20 tumor‐bearing animals, three separate experiments)." (PMID 33587338, 2021). "On the other side, previous publications reported that CD8+ were more frequent in AR+ than AR− tumours, in contrast to our study which showed that neither CD8 nor CD4 were statistically different between AR+ and AR− tumours." (PMID 35047068, 2021). "Our results showed that the percentage of CD45+CD4+ cells in the untreated NCG-HuPBL ATL mice was higher than that in the untreated NCG-HuPBL mice (NCG mice engrafted with PBMCs only, no tumor)." (PMID 34162832, 2021). "The definitions of positivity of STAT1, PD-L1, CD4, and CD8 were defined as positive expression on ≧ 1% of tumor cells or non-tumor cells, respectively." (PMID 34758826, 2021). "We found that the CD4+ T and CD8+ T cells were more abundant and that MDSCs were present in lower numbers in the non-metastatic 67NR tumours than in the metastatic 4T1 tumours." (PMID 33795809, 2021). "In contrast, SLC7A7 expression was not significantly correlated with tumor purity or infiltrating levels of CD8 + T cells, CD4 + T cells or neutrophils in UVM." (PMID 33632211, 2021). "PD‐L1 staining as well as the presence and absence of CD4+ and CD8 + TILs were used to show the tumor immune microenvironment feature." (PMID 33210451, 2021). "Unlike the results in the spleen, in the tumor site, a significant increase was seen in the percentage of CD3+ CD4+ TILs compared to other groups." (PMID 34282215, 2021).
tumor (continued). "Weighted correlation network analysis (WGCNA) resulted in the identification of six gene clusters (modules) that showed correlations in gene expression patterns between macrophages, CD4+ and CD8+ T cells originating from tumor and non-tumor tissue." (PMID 33918618, 2021). "Immunophenotypically, all tumour cells are positive for CD30 and negative for ALK and show variable expression of one or more T cell markers, such as CD3 and CD4." (PMID 33131026, 2021). "CD4(2/20) and B cell markers, like CD20(1/20) and CD79α(1/20) were positive in scattered tumor cells; whereas CD5 was negative in all cases." (PMID 34895266, 2021). "Herein we report that CD4+ and CD8+ T cells co-expressing KLRG-1 and CD57 were present in peripheral blood, tumor, and invaded and non-invaded lymph nodes from patients with untreated BC." (PMID 34386013, 2021). "More interestingly, after combination therapy, CD4+ and CD8+ T cells were significantly upregulated in the tumor microenvironment, and no significant increase in Treg cells was observed." (PMID 33391476, 2021). "In this setting, the B6 CD4+ T cells were reactive to BALB/c DC-derived alloantigens but not the B6 host; they failed to inhibit tumor growth and progression." (PMID 34625113, 2021). "The frequency of CD4+CD39+ TILs, which likely contain the Tregs were significantly higher in the tumor regardless of their CD103 expression." (PMID 34680397, 2021). "In contrast to the DCs treated with control tumor lysate, which increased the proportion of conventional FoxP3+ CD4 Tregs, the PAM-treated tumor lysate did not potentiate the Treg-inducing capacity of DCs." (PMID 33915703, 2021). "Anti-tumor effects of gCpG based vaccine were partially reduced as the lack of CD4+ T cells, while depletion of CD8+ T abrogated the anti-tumor efficacy of the vaccine, indicating that gCpG based vaccine controlled tumor growth by CD8+ T cells." (PMID 34794428, 2021). "In agreement with a previous study, this therapy also failed to induce infiltration of CD4+ and CD8+ T cells into the tumor." (PMID 33408092, 2021). "The CD4+ and CD8+ distribution within the different regions of the tissue was homogeneous with no signs of exclusion from the tumour parencyhma or different stroma regions." (PMID 33917832, 2021). "The results showed that exposure to PcrV did not significantly affect the percentages of CD4+ and CD8+ T cells, NK cells, or MDSCs in tumor tissues." (PMID 34900687, 2021). "Using Cd4-Tgfbr2dn mice, it was shown that TGF-β signals do not modify the expression of activation markers, such as CD69 and CD44 on CD8 tumor infiltrating T lymphocytes (TILs)." (PMID 34302795, 2021). "The expression level of PYCR1 was negatively correlated with tumor purity and has significant positive correlations with dendritic cells, but not with the infiltration levels of CD8+ T cells, CD4+ T cells, B cells, macrophages, and neutrophil." (PMID 34868460, 2021). "T-cell-derived tumor cells are positive for surface CD3+, CD5+, CD4+, or CD8+, or negative for both." (PMID 34830926, 2021). "Compared to tumor from WT group, the HDAC2-KO group had a higher percentage of CD45+ lymphocytes, CD3+, and CD8+ T cells, but not CD4+ population or CD4+FOXP3+ Treg cells." (PMID 34365463, 2021). "While CD4+ and CD8+ cells constituted a greater percentage of the tumor, there was no general systemic effect on CD4+ or CD8+ percentages in the thymus, spleen or blood." (PMID 34375938, 2021). "First, to test the impact of tumor cell-derived antigens, we pulsed GM-DCs with or without B16F1 tumor cell lysates and added them to BALB/c CD4+ T cell cultures." (PMID 34625113, 2021). "Helper T lymphocytes (CD4+) mediate antitumor immunity; however, in HNSCC, the prognostic significance of their presence in the tumor microenvironment is not yet settled." (PMID 34692375, 2021).
tumor (continued). "In contrast, treatment with an isotype-control antibody, or depletion of CD4+ T cells, TCRγδ+ T cells, NK cells, or Gr-1+ myeloid cells, did not prevent SCC tumour rejection." (PMID 33925140, 2021). "Unlike in tumor cells, there were no significant changes of CD45+, CD3+T, CD4+T, CD8+T proportion in peripheral blood in the late phase treatment experiment for both BA9 and BT942." (PMID 34824364, 2021). "In general, foreign antigens are presented to stimulate CD4+ T cells via the MHCII-mediated pathway, not CD8+ T cells which are primarily responsible for the anti-tumor immune response." (PMID 33824314, 2021). "The expression level of ACAD11 was positively correlated with tumor purity and the infiltration levels of CD8+ T cells and B cells, but not with the infiltration levels of CD4+ T cells, dendritic cells, macrophages, and neutrophil." (PMID 34868460, 2021). "Although the combination therapy did not prolong survival, tumor-infiltrated CD8 T and CD4 T cells were significantly increased in the combination groups." (PMID 35111150, 2021). "In this scenario, the anti-tumor response of CD26hi T cells was superior to other CD4 T-cell subsets such as TH17 and bulk CD4+ T cells and did not require CD8+ T cells indicative of a direct tumor-lysing capacity." (PMID 34885056, 2021). "We observed roughly double CD4+ and triple the CD8+ lymphocytic infiltrates in transplanted vs. spontaneous UPS tumours, but these differences were not statistically significant (p = 0.48 and p = 0.20, respectively)." (PMID 34242269, 2021). "To identify the T-cell subtype responsible for spontaneous metastasis, we backcrossed mice lacking CD4+ T or CD8+ T cells into the BALB/c background and evaluated tumour formation." (PMID 33795809, 2021). "Thus, lower level of IFN-γ/IL-2 producing CD4+ T cells of IN_in_r1-immunized mice may have indicated higher levels of CD4+ T cells producing IFN-γ/TNF-α, with the latter, or both events, contributing to a better protection of these mice against tumor challenge." (PMID 34199989, 2021). "Comparing tumour and non-tumour diseased tissue, we observed a modest increase in DPP4 expression by CD4+ T cells (CD45+ CD3+ CD4+ CD8− NK1.1−) and NK cells (CD45+ NK1.1+ CD3−)." (PMID 34771657, 2021). "Although TIL frequency and the content of CD8+, CD4+ and CD68+ immune cell populations were not altered, tamoxifen selected for ER+ tumor cells driven by the inflammatory NF-κB pathway with elevated stem cell and epithelial mesenchymal transition features." (PMID 34359625, 2021). "This phenotype applies in the same manner to the endogenous CD4+ and CD8+ T cells within the tumor but not the PLNs." (PMID 34335959, 2021). "Opposite, quantification of other key immune cells involved in anti-tumor responses, revealed that RvD1 did not significantly modify the infiltration of PMN, CD4, CD8 T cells, and MΦs." (PMID 33845864, 2021). "The analysis of the immunophenotypic markers shows that infiltration by CD4± and CD8± lymphocytes, both inside the tumour and in the stroma, has not any impact on survival." (PMID 33769181, 2021). "Intratumoral CD4+PD-1high T cells have a TFH cell phenotype that supports tumor growth with no TIM-3 expression, while CD4+PD-1low T cells that have an exhausted phenotype, express TIM-3 and display a reduced cytokine production and cell–signal transduction." (PMID 33562694, 2021). "We found that tumor infiltrated CD8+T cells were significantly increased 4 weeks after SNCP-125I brachytherapy, while CD4+T cell tumor infiltration showed no change (p=0.043)." (PMID 34136382, 2021). "In summary, we note that PDAC microenvironment is well infiltrated with effector CD4+ and CD8+, suggesting that the lack of anti-tumour response is not related to physical exclusion." (PMID 33917832, 2021). "We also observed a non-significant trend for higher levels of CD4+ CD25+ CD127- (Tregs) and CD8+ cells in letrozole-treated SSM3 tumours." (PMID 34602068, 2021).